TGS1 (trimethylguanosine synthase 1)
Description:
Catalyzes the 2 serial methylation steps for the conversion of the 7-monomethylguanosine (m(7)G) caps of snRNAs and snoRNAs to a 2,2,7-trimethylguanosine (m(2,2,7)G) cap structure. The enzyme is specific for guanine, and N7 methylation must precede N2 methylation. Hypermethylation of the m7G cap of U snRNAs leads to their concentration in nuclear foci, their colocalization with coilin and the formation of canonical Cajal bodies (CBs). Plays a role in transcriptional regulation.
Synonyms: PIMT; PIPMT; NCOA6IP
Tractability: Small molecule: a structure with a bound ligand is known; it has a high-quality binding pocket. PROTAC: ubiquitination databases record sites on it; its protein half-life has been measured.
Gene: Protein-coding gene on chromosome 8 (55,773,432 to 55,826,445, forward strand). Ensembl gene ENSG00000137574.
Subcellular location: Cytoplasm; Nucleus, Cajal body; Nucleus, nucleolus
Subcellular location (Human Protein Atlas): Cytosol
Pathways (Reactome):
Circadian clock: BMAL1:CLOCK,NPAS2 activates circadian expression; Expression of BMAL (ARNTL), CLOCK, and NPAS2; RORA,B,C and NR1D1 (REV-ERBA) regulate gene expression
Metabolism: Activation of gene expression by SREBF (SREBP); PPARA activates gene expression; Regulation of lipid metabolism by PPARalpha
Cellular responses to stimuli: Cytoprotection by HMOX1; Heme signaling
Developmental Biology: Transcriptional regulation of white adipocyte differentiation
Metabolism of RNA: snRNP Assembly
Organelle biogenesis and maintenance: Transcriptional activation of mitochondrial biogenesis
Gene Ontology:
Molecular function: protein binding; RNA cap trimethylguanosine synthase activity; RNA methyltransferase activity; methyltransferase activity
Biological process: 7-methylguanosine cap hypermethylation; ribonucleoprotein complex biogenesis; spliceosomal snRNP assembly
Cellular component: cytoplasm; cytosol; extracellular region; nucleus; nucleoplasm; small nuclear ribonucleoprotein complex; Cajal body; nucleolus
Genetic constraint (gnomAD): Loss-of-function variants: 49 observed, 70.1 expected, observed/expected ratio (o/e) 0.7, 90% interval 0.56 to 0.89. The upper end of that interval is the gene's LOEUF score, 0.89, which puts it in group 3 of 6, group 1 being the genes least tolerant of losing a copy. Missense variants: 896 observed, 898.52 expected, observed/expected ratio (o/e) 1, 90% interval 0.94 to 1.05. Synonymous variants: 308 observed, 309.48 expected, observed/expected ratio (o/e) 1, 90% interval 0.91 to 1.09.
Homologues: Orthologues: chimpanzee TGS1 (98% identical), macaque TGS1 (94% identical), dog TGS1 (82% identical), rabbit TGS1 (80% identical), guinea pig TGS1 (75% identical), mouse Tgs1 (74% identical), rat Tgs1 (73% identical), pig TGS1 (66% identical), tropical clawed frog tgs1 (48% identical), zebrafish tgs1 (37% identical), Caenorhabditis elegans tgs-1 (21% identical), Drosophila melanogaster Tgs1 (19% identical).
Diseases named in the same sentence as TGS1 in open-access papers:
TGS1 is named in the same sentence as 22 diseases in open-access papers, as found by Europe PMC text mining. Sharing a sentence is not in itself a finding about the gene and the disease. The quoted sentences say what the papers report.
tuberculosis (5 papers, 2018 to 2024). A chronic, recurrent infection caused by the bacterium Mycobacterium tuberculosis. "Additionally, this study established a link between reduced lnc- TGS1–1 expression and the prevalence of thrombocytopenia in tuberculosis patients receiving anti-TB medication." (PMID 35457250, 2022). "Another study in China examined 467 tuberculosis patients and 473 healthy controls, and lnc-AC145676 and lnc-TGS1–1 were analyzed." (PMID 35457250, 2022). "Expression differences of other transcripts, like TGS1 and CYP26B1 (that are differentially expressed in tuberculosis and juvenile idiopathic arthritis, respectively) could be related to neutrophil responses to intravascular perturbations during IA." (PMID 30593281, 2018). "Under the response of isoniazid, tgs1 was found to be significantly up-regulated in MDR-Mtb, thus indicating that this gene could represent a significant breakthrough in the monitoring and treatment of drug resistant tuberculosis in the future." (PMID 39845031, 2024). "Studies on Mycobacterium tuberculosis (Mtb) have reported that the expressions of lnc-TGS1-1 and lnc-AC145676.2.1-6 were downregulated in tuberculosis (TB) patients, and that PCED1B-AS1, lncRNA XLOC_012582, and ENST00000427151 could be used as early diagnostic biomarkers for Mtb infections." (PMID 39057090, 2024).
diabetes (2 papers, 2022). "We propose that these observations can be used as a stepping-stone for the design of novel strategies focused on TGS1 as a therapeutic target for the treatment of diabetes." (PMID 35041827, 2022). "Also, the gene expression of hspX, tgs1, and tgs5 was upregulated, and after diabetes induction, blood glucose levels were >200 mg/dl." (PMID 36776550, 2022). "Together, these data support the concept that elevation of TGS1 levels in β-cell and insulin-sensitive tissues could be a common marker of hyperglycemia/insulin resistance in diabetes." (PMID 35041827, 2022). "Our results suggest that an increase in TGS1 levels could play a beneficial role in the adaptation of β-cell to insulin resistance and diabetes." (PMID 35041827, 2022). "The mechanisms for the increase in TGS1 levels in models of diabetes are not completely identified, but we show that insulin in a paracrine fashion is involved." (PMID 35041827, 2022).
hyperglycaemia (2 papers, 2022 to 2023). "Given the important role of snRNAs and snoRNAs in β-cells and in pancreas development and the association between TGS1 upregulation in hyperglycemia and the regulation of hepatic glucose output, we decided to study TGS1 in β-cells." (PMID 35041827, 2022). "Recent data showed that two-month-old β-cell-specific TGS1 knockout mice (βTGS1KO) exhibit hyperglycaemia, decreased serum insulin levels, and impaired glucose tolerance." (PMID 37175791, 2023). "The present work adds TGS1 as a novel regulator of β-cells from mouse models of hyperglycemia and in human islets from T2D." (PMID 35041827, 2022). "To test how TGS1 regulates β-cell apoptosis, we performed RNA-Seq in islets from βTGS1KO before the development of hyperglycemia and reduction of β-cell mass (1 month-old)." (PMID 35041827, 2022). "These experiments showed that TGS1 inactivation in mouse β-cells results in hyperglycemia and glucose intolerance as a result of a reduction in β-cells mass." (PMID 35041827, 2022). "Consistent with the previous data, TGS1 levels in β-cells are elevated in conditions of HFD-induced insulin resistance and hyperglycemia (mice fed HFD for 8 weeks)." (PMID 35041827, 2022).
acute myeloid leukemia (1 paper, 2022). Acute myeloid leukemia (AML) is a group of neoplasms arising from precursor cells committed to the myeloid cell-line differentiation. "Importantly, TGS1 knockdown in acute myeloid leukemia results in the downregulation of oxidative phosphorylation (OXPHOS) with a consequent oxidative stress." (PMID 36239357, 2022).
Insulin resistance (1 paper, 2022). Increased resistance towards insulin, that is, diminished effectiveness of insulin in reducing blood glucose levels. "In conclusion, the present work identifies TGS1 as an important regulator of β-cells mass and function and demonstrates that this enzyme is important for adaptation to insulin resistance." (PMID 35041827, 2022). "Furthermore, higher TGS1 levels were previously observed in the soleus muscle of rats exposed to high sucrose diet-induced insulin resistance." (PMID 35041827, 2022).
lung adenocarcinoma (1 paper, 2022). A carcinoma that arises from the lung and is characterized by the presence of malignant glandular epithelial cells. "We therefore eliminated TGS1 function in H1299 lung cancer cells and lung adenocarcinoma-derived tumor organoids by enzymatic inhibition or transient siRNA-mediated knockdown." (PMID 35484160, 2022).
lung carcinoma (1 paper, 2022). "Altogether, our data demonstrate that loss of TGS1 function results in the formation of extended G-rich telomere single-strand protrusions in standard and advanced preclinical lung cancer model systems." (PMID 35484160, 2022). "Our telomere-strand-specific DNA-FISH data show that acute depletion of TGS1 does not result in elongation of both telomere single strands in lung cancer cells." (PMID 35484160, 2022). "We therefore tested whether TGS1-mediated 2,2,7-TMG capping of hTR promotes telomerase-dependent TMM by restricting the formation of recombinogenic G-rich telomere-strand substrates that engage in ALT in telomerase- positive lung cancer cells." (PMID 35484160, 2022).
osteosarcoma (1 paper, 2023). A usually aggressive malignant bone-forming mesenchymal neoplasm, predominantly affecting adolescents and young adults. "To begin to investigate a role for TGS1 and TMG-capped mRNAs in canine sarcoma, we determined the effect of TGS1 downregulation on the proliferation and translation capacity of the OSCA-40 canine osteosarcoma." (PMID 37386121, 2023).
sarcoma (1 paper, 2023). A usually aggressive malignant neoplasm of the soft tissue or bone. "The evidence documents TMG-capped mRNAs are hallmarks of the investigated neoplasms and synergy between TGS1 specialized translation and canonical translation is involved in sarcoma recovery from mTOR inhibition." (PMID 37386121, 2023). "TGS1 failure prevented the anchorage-independent growth of osteo- and hemangio-sarcomas and curtailed sarcoma recovery from mTOR inhibition." (PMID 37386121, 2023). "The results from three representative canine sarcomas agreed that TGS1 and RHA downregulation inhibited anchorage-independent growth." (PMID 37386121, 2023). "Studies have shown TGS1 hyper methylates cap of several selenoprotein mRNAs for eIF4E-independent translation in transformed human cells, setting a precedent to investigate TGS1 activity in sarcoma explants." (PMID 37386121, 2023). "This study investigated whether TMG-capped mRNAs exist and whether TGS1 activity plays a role in promoting anchorage-independent growth in three representative canine sarcomas." (PMID 37386121, 2023). "As a result, the cumulative downregulation of TGS1 required TMG-cap-downregulation and mTOR inhibition and prevented recovery from mTOR inhibitor of all 3 tested sarcomas." (PMID 37386121, 2023).
spinal muscular atrophy (1 paper, 2020). A motor neuron disease that affect the muscles, and characterized by muscle weakness and atrophy resulting from progressive degeneration and irreversible loss of the anterior horn cells in the spinal cord (i.e., lower motor neurons) and the brain stem nuclei. "Previous studies have shown that TGS1 binds the Survival Motor Neuron (SMN) protein, whose deficiency causes spinal muscular atrophy (SMA)." (PMID 32453722, 2020).
Thrombocytopenia (1 paper, 2022). A reduction in the number of circulating thrombocytes. "Moreover, the lower expression of lnc-TGS1-1 is capable of indicating the development of thrombocytopenia after treatment." (PMID 36311754, 2022). "Furthermore, the downregulation of lnc-TGS-1 is related to thrombocytopenia during TB treatment." (PMID 36311754, 2022).
type 2 diabetes (1 paper, 2022). "Here, we show that TGS1 is upregulated by insulin and upregulated in islets of Langerhans from mice exposed to a high-fat diet and in human β-cells from type 2 diabetes donors." (PMID 35041827, 2022).
cancer (5 papers, 2021 to 2024). A tumor composed of atypical neoplastic, often pleomorphic cells that invade other tissues. "Ultimately, the goal in the field is to define critical intervention points, such as the inhibition of PAPD5 and potentially TGS1, that can be targeted to ameliorate deficiencies in telomere maintenance or to inhibit telomerase activity in cancer cells." (PMID 38108475, 2023). "The results suggest therapeutic targeting of TGS1 activity in cancer is ripe for future exploration." (PMID 37386121, 2023). "TGS1 is enriched in CBs, and like TCAB1, when TGS1 is depleted, TR localizes to nucleoli increasing its levels in human cancer cells." (PMID 38108475, 2023). "Together, our data indicate that TGS1 has a role in antagonizing the activation of the ALT pathway in telomerase-positive cancer cells." (PMID 35484160, 2022). "Therapeutic targeting of TGS1 activity in cancer is ripe for future exploration." (PMID 37386121, 2023). "Together, this demonstrates that the S-adenosylmethionine analog sinefungin is an efficient antagonist of TGS1-dependent 2,2,7-TMG capping of hTR in monoclonal cancer cell lines but also in patient-derived 3D cell culture model systems." (PMID 35484160, 2022). "This identifies TGS1-dependent 2,2,7-TMG of hTR as a novel regulator of telomere single-strand homeostasis in human cancer cells." (PMID 35484160, 2022). "Yet-to-be-determined are potential roles for TGS1 and TMG-capped mRNAs in neoplastic growth, which could have important implications for understanding the mechanisms of cancer progression and identifying potential targets for therapy." (PMID 37386121, 2023). "Our data highlight a central role for TGS1-dependent 2,2,7-TMG capping of hTR to assure selective, telomerase-dependent telomere maintenance and restrict the formation of telomeric substrates that lead to aberrant ALT in telomerase-positive cancer cells." (PMID 35484160, 2022). "Here the authors show that Trimethylguaonsine Synthase 1 (TGS-1) – dependent trimethylguanosine capping of the RNA component of the human telomerase complex has an important role in directing telomere dependent telomere maintenance and suppressing the ALT pathway in cancer cells." (PMID 35484160, 2022). "However, the role of human TGS1 in controlling telomere-maintenance pathways and telomere-strand homeostasis in cancer cells is not known." (PMID 35484160, 2022).
infection (5 papers, 2011 to 2024). The state of being infected such as from the introduction of a foreign agent such as serum, vaccine, antigenic substance or organism. "In our hypoxic THPM model, tgs1 (Rv3130c), Rv3088 (tgs4), Rv1760, Rv3371 and Rv3087 (data not shown for this gene) were found to be highly up-regulated at 72 h after infection." (PMID 21731490, 2011). "hspX and tgs1 are regulated in hypoxia, multiple-stress model, macrophage infection, and dormancy." (PMID 37237755, 2023). "lipY, tgs-1, and icl-1 gene expression may be crucial in the transition from active growth to a dormancy state generated during infection." (PMID 36144423, 2022).
tumor (3 papers, 2018 to 2023). "Studies are warranted given many reports of RHA and JUND dysregulation in neoplasms and the important role we have identified for TGS1 in recovery from mTOR inhibition." (PMID 37386121, 2023). "We found that the association of telomeres to the remaining CBs was significantly reduced, both in sinefungin-treated or TGS1- knockdown model H1299 cells and tumor organoids." (PMID 35484160, 2022).
TGS1 also shares sentences with these, for which no sentence is quoted: breast carcinoma (1 paper); Glucose intolerance (1); Granuloma (1); hepatocellular carcinoma (1); juvenile idiopathic arthritis (1); postmenopausal osteoporosis (1); psoriasis (1).